EZH2 (enhancer of zeste 2 polycomb repressive complex 2 subunit)
Diseases named in the same sentence as EZH2 in open-access papers (continued):
Sharing a sentence is not in itself a finding about the gene and the disease.
lung adenocarcinoma (continued). "Furthermore, EZH2 is a direct target of miR-26a in docetaxel resistance cells, which could significantly suppress proliferation, facilitate apoptosis, inhibit the metastasis ability, and reverse EMT to mesenchymal–epithelial transition in lung adenocarcinoma cells." (PMID 33014831, 2020).
neuroblastoma (76 papers, 2011 to 2025). Neuroblastoma (NB) is the most common solid, extracranial childhood tumor. "Consistently, an increase in EZH2 expression is significantly associated with poor outcome in patients with neuroblastoma." (PMID 36831211, 2023). "The epigenetic inactivation of RUNX3 expression, concomitant with the chromosome loss of 1p36 in neuroblastomas, is mediated at least in part by the enhancer of zeste 2 (EZH2)." (PMID 36831211, 2023). "In another study, the overexpression of EZH2 in neuroblastoma was found to be associated with poor patient prognosis, and PRC2 mediated the silencing of tumor suppressor genes like CASZ1 through epigenetic changes." (PMID 31920530, 2019). "LncRNA NBAT1 (also called CASC14), the expression of which is decreased in neuroblastoma, functionally interacts with PRC2 member EZH2 and controls the expression of target genes via the loss of H3K27me3 from their promoter regions, resulting in neuroblastoma development." (PMID 32366932, 2020). "The loss of heterozygosity and/or EZH2-mediated H3K27me3 modification can silence the CASZ1 gene in tumor samples from patients with a poor prognosis of neuroblastoma (NB)." (PMID 38053207, 2023). "The pharmacological inhibition of histone‐lysine N‐methyltransferase EZH2, a crucial epigenetic regulator, reprograms mesenchymal neuroblastoma cells, leading to the re‐expression of ST8SIA1." (PMID 40620486, 2025). "We also confirmed previous reports that the CHLA-90 and SK-N-MM models of ATRX IFF neuroblastoma were sensitive to the EZH2 inhibitor tazemetostat." (PMID 41380652, 2025). "Consistently, the expected H3K27me3 recovery upon KDM6B inhibition is also counterbalanced by the decrease in EZH2 expression in neuroblastoma." (PMID 41085408, 2025). "Summarizing both articles, reduced MEG3 levels and increased EZH2 levels form a feedback loop that promotes the development of neuroblastoma." (PMID 38473229, 2024). "EZH2 inhibition facilitated MYCN binding to the TERT promoter in neuroblastoma cells with long telomeres." (PMID 38837897, 2024). "To address this, we used tazemetostat for 3 weeks to inhibit EZH2 in two neuroblastoma cell lines with long telomeres containing doxycycline-inducible MYCN transgene (SKNMMMYCN and SKNJCIMYCN)." (PMID 38837897, 2024). "Of note, p75NTR (also known as NGFR), which is a representative marker of favorable prognosis in patients with neuroblastoma, is also silenced by EZH2." (PMID 36831211, 2023). "The rationale is that MYCN upregulates EZH2, leading to the inactivation of a tumor suppressor program in neuroblastoma, while ATRX in-frame fusion neuroblastoma is sensitive to EZH2 inhibition." (PMID 36675163, 2023). "Recent research has demonstrated that ATRX in-frame fusion neuroblastomas are sensitive to the enhancer of zeste homolog 2 (EZH2) inhibition by modulating neuronal gene signatures." (PMID 37190157, 2023). "Similar results were obtained in MYC-driven SK-N-AS cells, supporting that EZH2 globally sustains MYC(N) protein stability in neuroblastoma cells." (PMID 35013218, 2022). "The differential efficacy of EZH2 inhibitors in neuroblastoma tumor cell lines prompted us to further evaluate Ezh2 regulation of MYCN in mice." (PMID 35013218, 2022). "Using neuroblastoma and small cell lung carcinoma as model systems, we herein identify a previously underappreciated crosstalk between EZH2 and MYC(N) in regulation of tumor formation." (PMID 35013218, 2022). "EZH2 inhibition results in the reduced proliferation of neuroblastoma cell lines and decreased tumor growth." (PMID 35681734, 2022). "Administration of tamoxifen (TAM) results in creER recombinase-mediated Ezh2 deletion in peripheral neural crest cells that give rise to neuroblastoma." (PMID 35013218, 2022). "The fact that the methyltransferase-inactive EZH2 is capable of modulating MYC(N) stability prompted us to examine its functional relevance in MYC(N)-driven neuroblastoma cells." (PMID 35013218, 2022).
neuroblastoma (continued). "Here, the authors use neuroblastoma and small cell lung carcinoma model systems and reveal the crosstalk between EZH2 and MYC(N) in the regulation of tumour formation." (PMID 35013218, 2022). "We first treated neuroblastoma BE2C cells with the selective EZH2 inhibitor EPZ5687 or GSK343 and the BIRC5 inhibitor YM155." (PMID 36612203, 2022). "In this study, we identified a 27-gene signature centered on EZH2 across many types of cancers, including neuroblastoma, which is targeted by miR-34." (PMID 36612203, 2022). "We first performed Ezh2 knockdown in primary neuroblastoma cells isolated from the TH-MYCN transgenic mice." (PMID 35013218, 2022). "Taken together, these data suggest that EZH2 depletion induces MYC(N) degradation not only in neuroblastoma cells but also in other cancer cells overexpressing either the MYCN or MYC oncogene." (PMID 35013218, 2022). "Mono-, di- and tri-methylation at Histone 3 Lysine 27 by the HMT EZH2 is known to be specifically increased in neuroblastoma, particularly in MYCN amplified tumours, and also associated with poor patient outcome." (PMID 34064704, 2021). "Chen and colleagues showed that CRISPR-Cas9 knockout of EZH2 in neuroblastoma resulted in decreased cell viability." (PMID 34206917, 2021). "Enhancer of Zeste Homolog 2 (EZH2) is known to play a key role in supporting the malignant phenotype in several cancer types and knockdown of EZH2 has been shown to decrease tumorigenesis in neuroblastoma cells." (PMID 33690617, 2021). "As a result, EZH2 inhibitors have been investigated in a number of malignancies, including neuroblastoma." (PMID 34064704, 2021). "A phase II study is currently investigating the use of EPZ6438 in EZH2 mutant tumours, including neuroblastoma (NCT03213665)." (PMID 34064704, 2021). "A recent study identified a 37-gene signature of EZH228, which is repressed by EZH2 and silenced in MYCN-amplified high-risk neuroblastoma." (PMID 34893606, 2021). "EZH2 has been independently shown to repress tumor suppressor genes in neuroblastoma, including CASZ1, RUNX3, NGFR, and CLU." (PMID 32537432, 2020). "Our study also rationalizes the combined pharmacological targeting of G9a and EZH2 for neuroblastoma in the future." (PMID 32537432, 2020). "Considering that NBAT-1 is expressed at low levels in high-risk neuroblastoma, NBAT-1 acts as a scaffold for EZH2 recruitment and represses NBAT-1/EZH2 target genes, which are involved in neuroblastoma progression." (PMID 29458374, 2018). "Both genetic and chemical inhibition of EZH2 in MYCN-amplified neuroblastoma mouse models resulted in decreased tumor burden." (PMID 30326621, 2018). "A recent CRISPR-Cas9 screening of MYCN-amplified neuroblastoma discovered preferential dependency on EZH2." (PMID 30326621, 2018). "To this end, we first expressed miR-124 in mouse neuroblastoma Neuro2a (N2a) cells and showed that this treatment was sufficient to up-regulate a significant fraction of neuron-specific Ezh2 target genes." (PMID 24878960, 2014). "Expression of miR-124 in a neuroblastoma cells line was sufficient to up-regulate a significant fraction of nervous system-specific Ezh2 target genes." (PMID 24878960, 2014). "All the other investigated primitive childhood tumors (rhabdomyosarcomas, neuroblastomas, Wilms’ tumors and rhabdoid tumors) stained positively for EZH2." (PMID 22809481, 2012). "Both ATRX IFF neuroblastoma cell lines showed sensitivity to RA as a single agent and their clonogenicity was further reduced with the addition of either tazemetostat or the EZH2 degrader MS1943, at doses sufficient to reduce H3K27me3 levels." (PMID 41380652, 2025). "Expression of EZH2, a transcriptional target of MYCN, is associated with neuroblastoma outcome, and inhibition of this histone methyltransferase by genetic or pharmacologic means, leads to neuroblastoma growth inhibition." (PMID 38992040, 2024).
neuroblastoma (continued). "Moreover, treating TERT-negative neuroblastoma cells with two other EZH2 inhibitors (UNC1999 and PF-06821497 acetate) induced the expression of TERT, confirming the role of PCR2 complex in repressing TERT locus in neuroblastoma cells with long telomeres." (PMID 38837897, 2024). "The histone-methylating polycomb repressive complex 2 (PRC2) is an additional critical mediator of gene expression in MYCN-amplified neuroblastoma and inhibition of one of the complex members, enhancer of zeste homolog 2 (EZH2), has antitumor activity in some murine models." (PMID 38820154, 2024). "As inhibiting EZH2 led to MYCN-induced TERT expression in neuroblastoma cells with long telomeres, we wondered whether inhibiting EZH2 facilitates MYCN binding to the TERT promoter." (PMID 38837897, 2024). "Notably, in high-risk MYCN-amplified neuroblastoma, H3K9 euchromatic histone lysine methyltransferase (EHMT) inhibitors in combination with EZH2 inhibitors exert immunomodulatory effects by inducing strong IFN-γ downstream responses." (PMID 39766049, 2024). "In addition, CASZ1, another candidate tumor-suppressor in neuroblastomas harboring 1p36, is also epigenetically inactivated by EZH2." (PMID 36831211, 2023). "Considering EZH2 as a potential epigenetic repressor of RUNX3, there could be a regulatory mechanism for the MYCN protein by mutually exclusive binding to oncogenic EZH2 or tumor-suppressive RUNX3 in neuroblastomas." (PMID 36831211, 2023). "We have shown that EZH2 plays an essential role in MYC(N) stabilization in neuroblastoma cells." (PMID 35013218, 2022). "Interestingly, neuroblastoma initiation in TH-MYCN mouse models involves sustained EZH2 expression and the suppression of PRC2 targets in MYCN-expressing sympathetic neuroblasts." (PMID 35681734, 2022). "In addition, we observed low H3K27me3 at the telomeres of ALT cases, which goes in line with a significantly lower protein and mRNA expression of EZH2 in ALT neuroblastomas compared to telomerase-activated tumors." (PMID 33627664, 2021). "The ganglioside GD2, well-established as an immunotherapy target in neuroblastoma, may also have promise in EwS, when combined with other agents such as all-trans retinoic acid, EZH2 inhibitor or antibody targeting HGF." (PMID 33919988, 2021). "Taken together, MEG3 and EZH2 could in the future be joint targets for the treatment of childhood neuroblastomas." (PMID 33061817, 2020). "It has been reported that high EZH2 expression is prognostic for poor clinical outcome in neuroblastoma patients and that EZH2-catalyzed H3K27me3 is responsible for transcriptional repression of several neuroblastoma tumor-suppressor genes, including CASZ1 GLU, RUNX3, and NGFR19." (PMID 30631055, 2019). "Interestingly, recent studies have provided evidence for an important role of the H3K27-specific methyltransferase EZH2 in neuroblastoma pathogenesis." (PMID 30631055, 2019). "In addition, Ezh2 activity has been shown to be critical for the growth of mouse neuroblastoma spheres in culture and for tumor development in the TH-MYCN mouse model." (PMID 30631055, 2019). "Finally, ChIP showed that hemagglutinin-tagged TSPYL2 co-existed with EZH2 in target promoters in neuroblastoma cells." (PMID 30051352, 2019). "In addition, EZH2 was found to be expressed in high levels in MYCN-amplified neuroblastomas, with MYCN binding at the EZH2 promoter, directly driving expression." (PMID 30326621, 2018). "Only two of the EZH2 mutation-positive individuals we report have developed malignancies; case 8 who carries a de novo missense mutation, A682T, in the SET domain, developed neuroblastoma and acute lymphoblastic lymphoma, both diagnosed at 13 months." (PMID 22190405, 2011). "Therefore, we hypothesized that the combination of RA with EZH2 inhibition may have an additive effective for ATRX IFF neuroblastoma." (PMID 41380652, 2025).
neuroblastoma (continued). "Notably, in terms of treatment, the utility of EZH2 inhibitors in neuroblastoma may in part be influenced by telomere maintenance mechanism." (PMID 38837897, 2024). "Our single-cell imaging of SH-SY5Y cells demonstrated that the levels of EZH2 positively correlated with both H3K27me3 and a JNK-impaired state, potentially in line with previous observations showing that EZH2 expression is increased in neuroblastoma and associated with a poor patient outcome." (PMID 36867694, 2023). "Similarly, the type 5 genes showed significant higher level in neuroblastoma with low EZH2." (PMID 35169119, 2022). "Furthermore, inhibiting EZH2 in neuroblastoma (NB) patients upregulates genes related to neuronal maturation, inducing apoptosis in ATRX in-frame fusion (IFF) NB cells." (PMID 39479502, 2024). "A previous study revealed that MYCN upregulates EZH2, leading to the inactivation of a tumor suppressor program in neuroblastoma; meanwhile ATRX in-frame fusion neuroblastoma is sensitive to EZH2 inhibition." (PMID 36675163, 2023). "The histone methyltransferase EZH2 shows increased expression levels in neuroblastoma and is induced by MYCN binding to the EZH2 promoter." (PMID 35681734, 2022). "Altogether, these results support that Ezh2 is indispensable for sustaining MYCN deregulation and maintaining MYCN-driven neuroblastoma in vivo." (PMID 35013218, 2022). "Consistently, knockdown of mouse Ezh2 by specific shRNAs led to a marked decrease in both MYCN protein levels and primary neuroblastoma cell growth." (PMID 35013218, 2022). "EZH2 is highly expressed in MYCN-amplified neuroblastoma, maintaining the tumor cells in an undifferentiated state, and EZH2 inhibition reduces neuroblastoma growth in vitro and in vivo." (PMID 35681734, 2022). "All these data argue that the EZH2-MYCN axis sustains MYCN expression and amplifies MYCN-dependent oncogenic programs to promote neuroblastoma progression." (PMID 35013218, 2022). "Another EZH2 inhibitor, EPZ6438 induced neuroblastoma cell differentiation through epigenetic modification of the TrkA promoter." (PMID 34064704, 2021). "In neuroblastoma, lncRNA Xist, which interacts with EZH2 to downregulate DKK1 by inducing H3 histone methylation, promotes neuroblastoma cell growth, proliferation, migration, and invasion via modulating H3 histone methylation of DKK1 in neuroblastoma." (PMID 34178980, 2021). "We utilized four long-term passage neuroblastoma cell lines and two patient-derived xenolines (PDX) to investigate the effects of the EZH2 inhibitor, GSK343, on viability, motility, stemness and in vivo tumor growth." (PMID 33690617, 2021). "Altered expression of PcG proteins, such as EZH2, SUZ12 and BMI1, are found in numerous cancer types, such as prostate, breast, liver and neuroblastomas, to name a few." (PMID 33912356, 2019). "Casz1 has been shown to interact with histones and recruit nucleosome remodeling and histone deacetylase complex, and Polycomb complex histone methytransferase subunits EZH2 to regulate gene transcription in HEK293T and neuroblastoma cells." (PMID 29467767, 2018). "In addition, new findings have demonstrated that aberrant up-regulation of EZH2 expression in neuroblastoma cells lead to silencing of several tumor suppressors, which contributed to the oncogenesis and maintenance of the undifferentiated phenotype of neuroblastoma tumors." (PMID 26378045, 2015). "Moreover, high EZH2 or DOT1L expression had prognostic significance independent of MYCN amplification status, age of diagnosis and International Neuroblastoma Staging System (INSS) disease stage." (PMID 39501501, 2024). "Interestingly, we also observed that inhibiting EZH2 derepressed TERT and induced expression in neuroblastoma cells with long telomeres, relative to the housekeeping gene HPRT." (PMID 38837897, 2024).
neuroblastoma (continued). "Combined blockage of EZH2 and HDAC1 with the appropriate inhibitors may be an effective treatment strategy for neuroblastoma cases with low MEG3 and high EZH2 levels." (PMID 38473229, 2024). "We focused on the ALK, IGF1, WNT, EZH2/PRC2, BET, CDK7, and CDK12/13 signaling pathways since they have been shown to be important during the normal development of sympathoadrenal cells and/or involved in neuroblastoma tumorigenesis." (PMID 35681734, 2022). "Depletion of EZH2 expression in multiple MYCN-amplified and -nonamplified neuroblastoma cells by specific sgRNAs or shRNAs caused minimal changes in MYCN mRNA levels." (PMID 35013218, 2022). "The growth inhibition observed for neuroblastoma cells raised the question whether sympathoadrenal cells and NESTIN-expressing cells would respond differentially to EZH2 inhibitors." (PMID 35681734, 2022). "We hypothesized that the EZH2 inhibitor, GSK343, would affect cell proliferation and viability in human neuroblastoma." (PMID 33690617, 2021). "In human neuroblastoma cells RUNX3 gene transcriptional activity has been shown to be under negative control by EZH2, the histone methyltransferase catalytic subunit of the polycomb repressive complex 2 (PRC2)." (PMID 34360553, 2021). "With regard to NGFR, the present study provides evidence that one mechanism by which VPA upregulates p75NTR expression involves the depletion of the PRC2 core component EZH2 and the consequent derepression of CASZ1, a neuroblastoma tumour suppressor and a positive regulator of NGFR." (PMID 32712736, 2020). "In the case of neuroblastoma, tumors with high amplification of MYCN show hyperactivation of PRC2-associated components such as EZH2, EED, and RBBP7 with respect to non-MYCN-amplified neuroblastoma cases." (PMID 31920530, 2019). "In neuroblastoma (NB), MYCN-induced upregulation of the H3K9 methyltransferases G9a and GLP as well as EZH2 can also inhibit IFN-γ-induced expression of CXCL9 and CXCL10." (PMID 39080807, 2024). "In neuroblastoma, G9a and GLP were found to have a positive correlation with MYCN expression, and increased H3K9me2 and H3K27me3 at the CXCL9, CXCL10, and CXCL11 chemokine cluster indicated the potential role of G9a, GLP, and EZH2 in maintaining a ‘cold’ tumor microenvironment." (PMID 39766049, 2024). "EZH2 is important for neuroblastoma cell survival by suppressing differentiation and tumor suppressors and for stabilizing the MYC oncoprotein, indicating that targeting EZH2 could be an alternative approach for neuroblastoma treatment." (PMID 36612203, 2022). "Importantly, pharmacological inhibition of EZH2 restored cell surface MHC-I in K-562 and cell lines representative of neuroblastoma, SCLC, and MCC, a neuroendocrine cancer recently shown to escape from immunotherapy through transcriptional downregulation of MHC-I genes." (PMID 31564637, 2019). "Depletion, but not enzymatic inhibition, of EZH2 induces robust MYC(N) degradation and inhibits tumor cell growth in MYC(N) driven neuroblastoma and small cell lung carcinoma." (PMID 35013218, 2022). "Since most MYCN-nonamplified neuroblastoma cells exhibited high MYC levels, we also inhibited EZH2 expression in SK-N-AS, SH-SY5Y, and SK-N-SH cells." (PMID 35013218, 2022). "The EZH2 inhibitor, tazemetostat, is currently under evaluation in pediatric patients with INI1-negative tumors or recurrent synovial sarcoma but has not been specifically investigated in patients with neuroblastoma (NCT02601937)." (PMID 30326621, 2018). "In addition, real-time RT–PCR demonstrated that other childhood malignancies including common acute lymphoblastic leukaemia (cALL) and neuroblastoma showed a significantly lower or no expression of CHM1 and EZH2, respectively." (PMID 21407224, 2011).